RNU6-989P (RNA, U6 small nuclear 989, pseudogene)
Gene: Small nuclear RNA gene on chromosome 2 (187,270,698 to 187,270,804, reverse strand). Ensembl gene ENSG00000199626.
Homologues: Orthologues: chimpanzee U6 (100% identical), macaque U6 (89% identical), rabbit U6 (83% identical), dog U6 (72% identical), guinea pig U6 (71% identical). Paralogues in human: RNU6-949P (84% identical), RNU6-142P (82% identical), RNU6-338P (82% identical), RNU6-1060P (81% identical), RNU6-242P (81% identical), RNU6-24P (81% identical), RNU6-348P (81% identical), RNU6-35P (81% identical), RNU6-41P (81% identical), RNU6-47P (81% identical), RNU6-621P (81% identical), RNU6-698P (81% identical), and 1286 more.